OVGP1 (oviductal glycoprotein 1)
Description:
Binds to oocyte zona pellucida in vivo. May play a role in the fertilization process and/or early embryonic development.
Synonyms: MUC9; OGP; CHIT5; EGP
Tractability: Antibody: UniProt predicts a signal peptide or a membrane-spanning region; its Gene Ontology location is reachable by antibodies, with medium confidence.
Gene: Protein-coding gene on chromosome 1 (111,414,319 to 111,427,735, reverse strand). Ensembl gene ENSG00000085465.
Subcellular location: Cytoplasmic vesicle, secretory vesicle
Subcellular location (Human Protein Atlas): Vesicles; Microtubules; Predicted to be secreted
Pathways (Reactome):
Reproduction: Interaction With Cumulus Cells And The Zona Pellucida
Gene Ontology:
Molecular function: chitin binding
Biological process: female pregnancy; carbohydrate metabolic process
Cellular component: cytosol; extracellular region; egg coat; perivitelline space; transport vesicle
Genetic constraint (gnomAD): Loss-of-function variants: 23 observed, 41.57 expected, observed/expected ratio (o/e) 0.55, 90% interval 0.4 to 0.78. The upper end of that interval is the gene's LOEUF score, 0.78, which puts it in group 3 of 6, group 1 being the genes least tolerant of losing a copy. Missense variants: 725 observed, 776.97 expected, observed/expected ratio (o/e) 0.93, 90% interval 0.88 to 0.99. Synonymous variants: 271 observed, 295.61 expected, observed/expected ratio (o/e) 0.92, 90% interval 0.83 to 1.01.
Homologues: Orthologues: chimpanzee OVGP1 (96% identical), macaque OVGP1 (83% identical), guinea pig OVGP1 (60% identical), mouse Ovgp1 (58% identical), rabbit OVGP1 (58% identical), pig OVGP1 (56% identical), dog OVGP1 (53% identical), Drosophila melanogaster Cht7 (29% identical), Drosophila melanogaster Cht10 (28% identical), Caenorhabditis elegans cht-1 (24% identical), Drosophila melanogaster Cht8 (24% identical), Drosophila melanogaster Cht4 (21% identical), and 36 more. Paralogues in human: CHIA (30% identical), CHIT1 (28% identical), CHI3L1 (27% identical), CHI3L2 (26% identical), CTBS (12% identical), CHID1 (9% identical).
Diseases named in the same sentence as OVGP1 in open-access papers:
OVGP1 is named in the same sentence as 19 diseases in open-access papers, as found by Europe PMC text mining. Sharing a sentence is not in itself a finding about the gene and the disease. The quoted sentences say what the papers report.
Infertility (4 papers, 2022 to 2024). "Future research using OVGP1 is likely to address the pathogenesis of infertility due to unexplained early fertilization defects and delayed fetal growth in early pregnancy." (PMID 37995271, 2024). "The current findings could be of significance to the field of infertility as a better understanding of the function of OVGP1 could improve the success rates of conventional IVF procedures by supplementing the capacitating medium currently used in fertility clinics with rHuOVGP1." (PMID 35972586, 2022).
ovarian carcinoma (3 papers, 2021 to 2025). A malignant neoplasm originating from the surface ovarian epithelium. "OVGP1: this has not been previously associated with MM, but is known as a tumor suppressor in ovarian cancer, where low OVGP1 expression correlates with poor prognosis." (PMID 40299486, 2025).
endometriosis (2 papers, 2020 to 2022). The growth of functional endometrial tissue in anatomic sites outside the uterine body. "Expression of OVGP1 is a marker of P4 action and conditions including endometriosis that results in P4 resistance result in persistent oviductal OVGP1 expression." (PMID 35563839, 2022).
colorectal cancer (1 paper, 2025). A primary or metastatic malignant neoplasm that affects the colon or rectum. "Traditionally, OVGP1 was considered to have a reproduction-specific function, but recent studies have revealed its unexpected involvement in various malignancies, including breast, ovarian, and colorectal cancers." (PMID 40299486, 2025).
endometrioid ovarian cancer (1 paper, 2022). "In the Pten/Apc model, it was shown previously that both OSE cells (based on the intrabursal injection of Ad-CMV-Cre) and FTE cells (based on the tamoxifen-induced activation of Ovgp1-iCreER) could serve as the cells-of-origin of endometrioid ovarian cancer." (PMID 35159108, 2022).
female infertility (1 paper, 2024). Diminished or absent ability of a female to achieve conception. "The KO mouse is fertile; however, the deletion of Ovgp1 (KO) in the golden hamster (Mesocricetus auratus) leads to female infertility." (PMID 39794998, 2024).
glass (1 paper, 2025). "Thus, OVGP1 was significantly associated with chronic pain and disorders of parathyroid glass (FDR < 0.05)." (PMID 40299486, 2025).
invasive carcinoma (1 paper, 2025). A carcinoma that is not confined to the epithelium, and has spread to the surrounding stroma. "Some markers of tubal differentiation present in the endosalpingiosis such as tubulin and OVGP1 are diminished in the invasive carcinoma, which retains expression of WT1, PAX8." (PMID 40940856, 2025).
male infertility (1 paper, 2016). The inability of the male to effect fertilization of an ovum after a specified period of unprotected intercourse. "Validation of class II high-impact variants within SPATA31E1, OVGP1, FOXP1, FBXO43 indicate further putative loci for stallion fertility, however the consequences of mutations on male infertility in human and mice are not yet known." (PMID 27079378, 2016).
myeloma (1 paper, 2025). "We validated that MM cell lines have markedly reduced OVGP1 levels, aligning with a potential tumor-suppressor role for OVGP1 in myeloma." (PMID 40299486, 2025).
ovarian serous borderline tumors (1 paper, 2022). "OVGP1 is also called mucin 9 (MUC9), which can be secreted at increased levels in the serum of women with ovarian serous borderline tumors and low-grade serous cancers." (PMID 36076202, 2022).
ovarian serous tumor (1 paper, 2019). A benign, borderline, or malignant epithelial tumor of the ovary characterized by the presence of neoplastic epithelial cells that, in well differentiated tumors, resemble the epithelial cells of the fallopian tube and, in poorly differentiated tumors, show anaplastic features. "The results were further validated by selected proteins of OVGP1, WT-1, and FOM3, which were highly expressed in the samples of the fallopian tube, ovarian epithelial inclusions, and ovarian serous tumors, but not in ovarian surface epithelia." (PMID 30949203, 2019).
serous adenocarcinoma (1 paper, 2022). An adenocarcinoma that is characterized by the presence of papillary patterns and cellular budding. "However, multiple lines of evidence from previous studies have rendered support to a tubal origin of these lesions (e.g., based on Pax8 or Ovgp1-based genetic targeting), in particular the serous adenocarcinoma." (PMID 35159108, 2022).
tumor (4 papers, 2013 to 2025). "Although the role of OVGP1 in the reproductive system is well established, its emerging importance in tumor biology highlights its broader function that extends beyond reproduction." (PMID 40299486, 2025). "Abnormal OVGP1 staining in the ovarian cortex was noted in at least one tumor from an eight-week old mouse." (PMID 23741457, 2013). "Future studies should explore whether OVGP1 interacts with immune cells in the bone marrow, such as T cells or macrophages, and whether its expression influences anti-tumor immunity." (PMID 40299486, 2025).
cancer (2 papers, 2021 to 2025). A tumor composed of atypical neoplastic, often pleomorphic cells that invade other tissues. "OVGP1 appears to modulate key processes, such as extracellular matrix (ECM) integrity and cell adhesion, both of which are essential for cancer cell migration and metastasis." (PMID 40299486, 2025).
OVGP1 also shares sentences with these, for which no sentence is quoted: infection (2 papers); bacterial infection (1); schizophrenia (1); serous ovarian cancer (1).